CD4 (CD4 molecule)
Diseases named in the same sentence as CD4 in open-access papers (continued):
Sharing a sentence is not in itself a finding about the gene and the disease.
primary progressive MS (7 papers, 2012 to 2024). "CD4+CCR5+ T cells were shown to have higher susceptibility to apoptosis in primary progressive multiple sclerosis and visceral leishmaniosis compared to CD4+CXCR3+." (PMID 32751139, 2020). "We conclude that, in contrast to cerebrospinal fluid CD20dim CD8+ T cells, B cells and CD20dim CD4+ T cells are reduced in cerebrospinal fluid of people with primary progressive multiple sclerosis with an ocrelizumab-associated depletion of circulating B cells and CD20dim T cells." (PMID 38385000, 2024). "In addition, in both PBMCs and CSF of untreated people with primary progressive multiple sclerosis, a relative over-abundance of CD4+ compared with CD8+ CD45RA− memory T cells associated with a higher ARMSS score." (PMID 38385000, 2024). "In the CSF of people with primary progressive multiple sclerosis, OCR treatment was associated with a lower proportion of B cells but a similar distribution of total and memory T cells for both the CD4+ and CD8+ population." (PMID 38385000, 2024). "In conclusion, the use of OCR therapy is associated with the reduction of B cells and also a decreased presence of particularly CD4+ CD20dim T cells in the CSF of people with primary progressive multiple sclerosis." (PMID 38385000, 2024). "In patients with MS, CD4 T cell metabolism has been shown to differ between patients with primary progressive MS (PPMS) and those with secondary progressive (SPMS) MS." (PMID 34721394, 2021). "Here, we showed that treatment of people with primary progressive multiple sclerosis with OCR not only depletes both B cells and CD20dim T cells in the PBMC fraction but is also associated with a significant reduction of total B cells and especially CD4+ CD20dim CD45RA− memory T cells in the CSF." (PMID 38385000, 2024). "To explore the clinical relevance of our findings, we correlated the proportions of PBMC and CSF B cells as well as CD20dim CD4+ and CD20dim CD8+ CD45RA− memory T cells to age and ARMSS score in untreated people with primary progressive multiple sclerosis." (PMID 38385000, 2024). "The objective of this study was to investigate regulatory T cells (Tregs) and monocytes; specifically, the expression of CTLA-4 (CD152) and FOXP3+ in CD4+CD25+ Tregs and the expression of CD40+ and CD192+ monocyte subpopulations in subjects with primary progressive multiple sclerosis (PPMS)." (PMID 38398067, 2024). "OCR-treated people with primary progressive multiple sclerosis had a lower proportion of CD20dim cells within the CSF CD45RA− memory CD4+ T-cell pool, which was not significantly lower within the CSF CD8+ CD45RA− memory T-cell pool." (PMID 38385000, 2024). "Since specifically the kinetics of CSF recruitment of B cells and CD20dim CD4+ T cells are affected by OCR, we conclude that these cell types are more likely to contribute to the therapeutic effects of OCR in people with primary progressive multiple sclerosis compared with CD8+ T cells." (PMID 38385000, 2024). "However, CCR5+, CXCR3+, CCR6+ and CCR4+ cells within the CD4+ CD45RA− memory T-cell pool of the CSF of OCR-treated people with primary progressive multiple sclerosis were all depleted for CD20dim T cells, which was not the case for the CD8+ memory T-cell pool." (PMID 38385000, 2024). "First, we analysed the relative numbers of B cells and both CD4+ and CD8+ memory (CD45RA−) T cells in paired PBMC and CSF samples from people with primary progressive multiple sclerosis without OCR treatment." (PMID 38385000, 2024). "Next, we compared the distribution of B cells and CD4+ and CD8+ CD45RA− memory T cells in PBMCs of people with primary progressive multiple sclerosis with versus without OCR treatment." (PMID 38385000, 2024).
protozoal infections (7 papers, 2006 to 2023). "Effective HAART helps eradicating opportunistic protozoal infection, and associated with the influx of CD4 positive cells into the lamina propria." (PMID 16509972, 2006). "This condition leads to severe CD4+ T-cell dysfunction and thus recurrent bacterial, viral and protozoal infections." (PMID 25748655, 2014). "In other protozoal infections of mice CD4+ effector T cells that co-produce IFN-γ and IL-10 have been identified." (PMID 19343213, 2009). "Although IL-10 can be produced by a variety of CD4 T-cell subsets, IL-10 production by using the Th1 subset has been shown to be required for attenuation of morbidity and immune-mediated pathology during primary murine malaria infection and other protozoal infections." (PMID 29097996, 2017).
sickle cell disease (7 papers, 2013 to 2024). Sickle cell anemias are chronic hemolytic diseases that may induce three types of acute accidents: severe anemia, severe bacterial infections, and ischemic vasoocclusive accidents (VOA) caused by sickle-shaped red blood cells obstructing small blood vessels and capillaries. "In addition, in polytransfused sickle cell disease patients, high levels of CXCR5+PD1+CD4+ T lymphocyte (TL) may be a biomarker for the inhibited functions of T cells." (PMID 35479938, 2022).
staphylococcal infection (7 papers, 2012 to 2025). An infection caused by Staphylococcus. "We previously showed that myeloid-derived suppressor cells (MDSC) expand during staphylococcal infections and support infection chronicity by inhibiting CD4+ T cell responses." (PMID 37480485, 2023). "Patients with S. aureus and HIV infections were much younger than those in non-HIV patients with S. aureus infection and the mean CD4 cell count was 95 cells/mm3, consistent with the reported threshold of 200 cells/mm3 as a risk factor for staphylococcal infections." (PMID 40784249, 2025). "It was shown that the number of CD3+, CD4+, CD8+, and CD19+ cells, as well as the CD4/CD8 index, changed in cases of intravaginal staphylococcal infection." (PMID 22611454, 2012). "Irrespective of single or coinfections, moDCs matured in response to IAV and/or staphylococcal infections, secreted a wide range of cytokines, and activated CD4+, CD8+ as well as double-negative T cells." (PMID 35249041, 2022). "The viability of CD4+ T cells in the spleen of infected wild type mice was equivalent to that of the control group suggesting that apoptosis of T cells is not a major process at this time point during staphylococcal infection." (PMID 30123776, 2018).
Stevens-Johnson syndrome (7 papers, 2007 to 2023). Stevens-Johnson syndrome is a limited form of toxic epidermal necrolysis characterized by destruction and detachment of the skin epithelium and mucous membranes involving less than 10% of the body surface area. "RashSAEs occurred in 12 of 196 (6%) women with a baseline CD4 count of≥250 cells/mm3 (including three cases of Stevens-Johnson Syndrome,all with CD4 counts of >350 cells/mm3) versus four of 114(4%) women with CD4 counts of <250 cells/mm3(RR = 1.7, 95% CI 0.6–5.3)." (PMID 21468300, 2011). "One non-pregnant subject on NVP was diagnosed with Stevens-Johnson syndrome 22 days after initiation of treatment; CD4 count at therapy initiation was 420 cells/mm3." (PMID 20838641, 2010).
Stillbirth (7 papers, 2009 to 2024). Death of the fetus in utero after at least 22 weeks of gestation. "In some studies, women with lower CD4 cell count have had a higher stillbirth risk." (PMID 22384039, 2012). "The associations between adverse birth outcomes (stillbirth, preterm birth, very preterm birth, and low birth weight) and the timing of maternal ART initiation, peripartum CD4 count, and HIV viral load were examined using logistic regression analysis." (PMID 39240844, 2024). "In a South African cohort study, women with CD4 cell counts <250 cells/mm3 had a two-fold increased risk of the adverse outcome (antenatal heath, miscarriage or stillbirth) compared to those with CD4 cell counts >500 cells/mm3." (PMID 22937874, 2012). "The median CD4 cell count at the time of the stillbirth delivery was 377 (range 104, 1953) cells/mm3 for those receiving HAART and 353 (range 44, 937) cells/mm3 for those not receiving HAART (p = 0.93)." (PMID 22384039, 2012). "While a low maternal CD4 count has been linked to an increased risk of stillbirth due to poor maternal immune status, we did not observe this association in our study." (PMID 39240844, 2024). "In the cohort conducted in four cities in sub-Saharan Africa, the risk of stillbirth was correlated with decreasing CD4 count but not with plasma viral load categorized into ≥100,000 copies/ml or less." (PMID 22937874, 2012). "The first of these stillbirths occurred at 32 weeks' gestation, in a woman with HIV RNA of 31,400 copies/mL and CD4 cell count of 511 cells/mm3, receiving ZDV for the previous 5 weeks." (PMID 22384039, 2012). "Verbal autopsies; maternal HIV, CD4 and HIV RNA testing; stillbirth HIV PCR testing; and placental pathology (blinded to HIV and treatment status) were performed." (PMID 22384039, 2012). "A study from Zambia has reported an inverse relationship between decreasing CD4 cell counts in HIV seropositive women and stillbirth (P =0.000)." (PMID 21501448, 2011). "A study in Tanzania found that elevated CD3 count, but not other markers such as CD4 or CD8 counts, was associated with stillbirth." (PMID 22937874, 2012).
synovial sarcoma (7 papers, 2016 to 2025). "Therefore, Ss infection appears to be associated with alterations in the memory subset distribution of CD4+ T cells." (PMID 29795573, 2018). "There was only one patient with ependymoma and one with synovial sarcoma, both with prolonged CD4 recovery." (PMID 38767518, 2024). "At the same time, we found that there was a significantly low infiltration of macrophages and CD4+ T lymphocytes in patients with metastatic synovial sarcoma in the GSE40021 dataset." (PMID 39735532, 2024). "To determine if Ss infection altered absolute numbers of T cells, we measured the absolute leukocyte count and absolute CD4+ and CD8+ T cell counts in INF and UN individuals." (PMID 29795573, 2018). "Given the prior use of HLA-DPB1-restricted MAGE-A3-specific CD4+ T cells, we analyzed mRNA expression of HLA-DPB1 and found that expression was significantly higher in UPS/MFS compare to leiomyosarcoma (p < 0.01) and synovial sarcoma (p < 0.001)." (PMID 31096717, 2019).
thrombosis (7 papers, 2013 to 2025). "We next investigated the functional role of T cells in venous thrombosis by comparing venous thrombus formation induced by vena cava ligation between animals treated with both anti-CD4 and anti-CD8 antibodies (depleted) or isotype matched antibodies (control)." (PMID 32121269, 2020). "In the bivariate analysis, study findings showed that prolonged immobility, platelets count, latest CD4 count, and ART line regimen had an association with deep venous thrombosis." (PMID 29370816, 2018).
thymic tumors (7 papers, 1996 to 2023). "The c-myc proto-oncogene linked to the mouse Thy-1 gene transcriptional unit predisposesmice to development of thymic tumors consisting predominantly of immature CD4+ CD8+cells." (PMID 8924763, 1996). "The majority (60%) of thymic tumors had a mixed phenotype expressing low-levels of CD4 and CD8 along with a combination of CD44 and CD25." (PMID 24586935, 2014). "The appearance of a thymic tumor at CD4+CD8+ stage suggest that transformation of T cells may have resulted in expression of the CD4 and CD8 molecules." (PMID 20976169, 2010). "CD4‐ and CD25‐positive cells were sorted from cultured T lymphocytes of a previously characterized experimental thymic tumor model composed of thymic nurse cells and abundant lymphoid stroma." (PMID 37220892, 2023). "Here, we demonstrated that using CD4 and CD25 sorting, adiponectin‐expressing Treg cells can be successfully harvested from cultured cells of an experimental murine thymic tumor model." (PMID 37220892, 2023). "Surprisingly, in RB-1B infected birds showing a thymus atrophy, we did not observe a decrease in T-cell number in the blood, but a T lymphocytosis of CD4+ and CD8+ cells." (PMID 29587836, 2018).
toxicity (7 papers, 2012 to 2024). The degree to which an agent can damage an organism. "In this cohort of nevirapine-treated women the presence of HBV or HCV was associated only to the development of mild liver toxicity, while the occurrence of moderate or severe hepatoxicity was correlated to a baseline CD4+ count > 250/mm3." (PMID 24708626, 2014). "High levels of CD4+ are known to be associated with nevirapine-induced liver toxicity, and in our cohort of nevirapine-treated women baseline levels of CD4+ > 250/mm3 were indeed correlated to the emergence of grade ≥ 2 ALT elevation." (PMID 24708626, 2014). "Here, reduced CD4+ count and CD4/CD8 ratio were observed as minor risk factors for liver toxicity." (PMID 39742334, 2024). "Interestingly, in our study low CD4+T cell count was a minor risk factor for liver toxicity since low CD4+T cell count showed a trend with hepatotoxicity only in the univariate analysis." (PMID 35658835, 2022). "However, nevirapine should not be initiated in women with a baseline CD4 cell count >250 cells/mm3 or in men with a CD4 cell count >400 cells/mm3 because these CD4 thresholds represent major risk factors for liver toxicity." (PMID 25908935, 2015). "In addition, smoking could decrease CD4+ T cells count and lowering of BMI hence a minor risk to liver toxicity." (PMID 35658835, 2022). "Our study showed that in an Asian HIV population, majority of whom had a low CD4 count but relatively normal CLCr, the proportion of patients who develop renal toxicity is low (2.2%; 5/226)." (PMID 22703627, 2012). "In HBV-infected women, after controlling for age, CD4+ count above or below 250/mm3 and hemoglobin level, a baseline HBV-DNA level > 10,000 IU/ml was significantly associated with the development of liver toxicity of any grade (HR:3.278, 95% CI 1.056-10.180, P = 0.040)." (PMID 24708626, 2014).
tularemia (7 papers, 2012 to 2020). Tularemia is an infection caused by the bacterium Francisella tularensis. "In addition, at least eight identified proteins were positively associated with peak tularemia-specific microagglutination titer or peak CD4+ activation following vaccination." (PMID 32722207, 2020). "At both days, peak CD4+ and tularemia-specific microagglutination titer were correlated with changes in proteins." (PMID 32722207, 2020). "Here, we employed elastic net regularized linear regression, which was successfully applied to similar contexts, to test metabolites as predictors of antibody response (peak tularemia-specific microagglutination titer) or peak CD4+ and CD8+ T cell activation." (PMID 32722194, 2020). "From this time onward, laboratory reports included comments suggesting consideration of possible tularemia if flow cytometry of peripheral blood showed an increased percentage of CD3+/CD4–/CD8– T cells or both CD3+/CD4–/CD8– and γδ T cells." (PMID 31538915, 2019). "The percentage of CD3+ T cells with the CD4–/CD8– phenotype was 19% in tularemia patients with differing disease presentations and 3% in control patients with a wide variety of infectious and noninfectious conditions." (PMID 31538915, 2019). "The time of symptom onset was known for 58 of 61 tularemia patients with CD3+/CD4–/CD8– T-cell percentages >8%." (PMID 31538915, 2019). "The median percentage of CD3+/CD4–/CD8– T cells in peripheral blood was higher in tularemia patients (19%, 95% CI 17%–22%) than in controls (3%, 95% CI 2%–3%)." (PMID 31538915, 2019). "The CD3+/CD4–/CD8– T cells increased a median of 7 days before tularemia serologic test results became positive." (PMID 31538915, 2019). "Seroconversion was documented in 53.1% (34/64) of patients with tularemia, many of whom had been treated for tularemia on the basis of raised CD3+/CD4–/CD8– T-cell percentages and were monitored until seroconversion or an alternative diagnosis was obtained." (PMID 31538915, 2019). "This tool has allowed investigators to characterize antigen-specific CD4+ T cells in various contexts and begin identifying the correlates of CD4-mediated protection from tularemia." (PMID 29284034, 2017). "Since CD4+ T cells are important for protection against tularemia, we evaluated the induction of antigen-specific CD4+ T cells by the subunit vaccine preparation." (PMID 23209745, 2012). "Animal studies have previously shown that B and T cell responses are important in the induction and regulation of an effective immune response to live tularemia vaccines; specifically, maintaining either CD4+ or CD8+ T cells in mice appeared to be essential for survival." (PMID 31878161, 2019). "Encouraged by local colleagues suggesting that raised γδ T-cell (and by inference CD3+/CD4–/CD8– T-cell) percentages could be used in earlier tularemia diagnosis, the Immunology Laboratory of České Budějovice Hospital (České Budějovice, Czech Republic) changed its reporting practices in 2003." (PMID 31538915, 2019). "To assess the relationship between proteome changes and humoral and cellular responses post-vaccination, we utilized CD4+, CD8+cell activation and tularemia-specific microagglutination titer we collected previously." (PMID 32722207, 2020). "Of these 39 total subjects, six subjects were positive responders for antibodies, CD4+ T cells, and CD8+ T cells against tularemia vaccines." (PMID 31878161, 2019). "The Spearman correlation coefficient of the plot of the CD3+/CD4–/CD8– T-cell and γδ T-cell percentages (in 48/64 tularemia cases where both parameters were known) was 0.830 (95% CI 0.679–0.906; p<0.0001)." (PMID 31538915, 2019). "Among our cohort, 61 (95.3%) tularemia patients and 36 (10.5%) controls had a peripheral blood CD3+/CD4–/CD8– T-cell percentage >8%." (PMID 31538915, 2019).
tularemia (continued). "To further characterize the role of DA lipids in the vaccine response, we generated correlation networks between log2 fold changes of 14 DA lipids, 22 cytokines, peak CD4/CD8 T cell activation, and tularemia-specific microagglutination using Spearman correlation." (PMID 32722213, 2020). "When we used 8% as the cutoff to define elevated CD3+/CD4–/CD8– T cells, we found this flow cytometry–based test was elevated >7 days before serologic test results became positive and had a sensitivity of 95% and specificity of 89.5% for distinguishing tularemia cases from other illnesses." (PMID 31538915, 2019). "In the subset of tularemia patients in whom an elevated CD3+/CD4–/CD8– T-cell percentage was detected while serology was still negative (58.6%, 34/58), the median delay from rise of CD3+/CD4–/CD8– T cells to positive serologic test result was 14 (95% CI 8–22) days." (PMID 31538915, 2019).